MYH10 (myosin heavy chain 10)
Description:
Cellular myosin that appears to play a role in cytokinesis, cell shape, and specialized functions such as secretion and capping. Involved with LARP6 in the stabilization of type I collagen mRNAs for CO1A1 and CO1A2. During cell spreading, plays an important role in cytoskeleton reorganization, focal contacts formation (in the central part but not the margins of spreading cells), and lamellipodial extension; this function is mechanically antagonized by MYH9. (Microbial infection) Acts as a receptor for herpes simplex virus 1/HHV-1 envelope glycoprotein B.
Synonyms: NMMHC-IIB; NMMHCB
Tractability: Antibody: UniProt places it where antibodies can reach, with high confidence; its Gene Ontology location is reachable by antibodies, with medium confidence. PROTAC: ubiquitination databases record sites on it; its protein half-life has been measured; a small molecule that binds it is known.
Gene: Protein-coding gene on chromosome 17 (8,474,205 to 8,632,303, reverse strand). Ensembl gene ENSG00000133026.
Subcellular location: Cell projection, lamellipodium; Cell membrane
Subcellular location (Human Protein Atlas): Actin filaments; Cytosol; Mitochondria
Pathways (Reactome):
Signal Transduction: RHO GTPases Activate ROCKs; RHO GTPases activate CIT; RHO GTPases activate PAKs; RHO GTPases activate PKNs
Developmental Biology: EPHA-mediated growth cone collapse; Sema4D induced cell migration and growth-cone collapse
Gene Ontology:
Molecular function: actin filament binding; ADP binding; ATP binding; microfilament motor activity; mRNA 5'-UTR binding; protein binding; RNA stem-loop binding; virus receptor activity; actin binding; cytoskeletal motor activity
Biological process: actin filament-based movement; actomyosin structure organization; mitotic cytokinesis; positive regulation of protein secretion; symbiont entry into host cell; regulated exocytosis; regulation of cell shape; vesicle fusion to plasma membrane; postsynaptic actin cytoskeleton organization
Cellular component: actomyosin; cell cortex; cell surface; cleavage furrow; cytoplasm; cytosol; extracellular exosome; midbody; myosin II complex; myosin II filament; nucleus; postsynaptic actin cytoskeleton; stress fiber; exocytic vesicle; myosin complex; myosin filament; axon; brush border; cytoplasmic side of plasma membrane; dendritic spine; glutamatergic synapse; growth cone; lamellipodium; neuromuscular junction; neuron projection; and 4 more
Genetic constraint (gnomAD): Loss-of-function variants: 44 observed, 227.31 expected, observed/expected ratio (o/e) 0.19, 90% interval 0.15 to 0.25. The upper end of that interval is the gene's LOEUF score, 0.25, which puts it in group 1 of 6, group 1 being the genes least tolerant of losing a copy. Missense variants: 1,459 observed, 2,305.2 expected, observed/expected ratio (o/e) 0.63, 90% interval 0.61 to 0.66. Synonymous variants: 763 observed, 873.2 expected, observed/expected ratio (o/e) 0.87, 90% interval 0.82 to 0.93.
Gene-disease validity (ClinGen):
ClinGen rates the evidence that MYH10 causes each of these diseases.
complex neurodevelopmental disorder with or without congenital anomalies (autosomal dominant): Definitive. A complex neurodevelopmental disorder that involves more than one phenotype associated with the central nervous system, including but not limited to intellectual disability, autism, and seizures (epilepsy), in addition to one or more structural or functional anomaly(ies) that develops prenatally.
Homologues: Orthologues: chimpanzee MYH10 (100% identical), macaque MYH10 (99% identical), rabbit MYH10 (99% identical), mouse Myh10 (98% identical), rat Myh10 (98% identical), dog MYH10 (97% identical), guinea pig MYH10 (96% identical), tropical clawed frog myh10 (91% identical), zebrafish myh10 (89% identical). Paralogues in human: MYH9 (76% identical), MYH11 (75% identical), MYH14 (66% identical), MYH7 (41% identical), MYH6 (40% identical), MYH3 (40% identical), MYH8 (40% identical), MYH7B (40% identical), MYH2 (40% identical), MYH1 (40% identical), MYH13 (39% identical), MYH4 (39% identical), and 32 more.
Diseases named in the same sentence as MYH10 in open-access papers:
MYH10 is named in the same sentence as 81 diseases in open-access papers, as found by Europe PMC text mining. Sharing a sentence is not in itself a finding about the gene and the disease. The quoted sentences say what the papers report.
glioma (8 papers, 2010 to 2024). A benign or malignant brain and spinal cord tumor that arises from glial cells (astrocytes, oligodendrocytes, ependymal cells). "For instance, MYH10 is overexpressed in glioma cells and implicated in cell migration and invasion, and also has a pro-tumorigenic effect in a murine lung cancer model." (PMID 35422813, 2022). "MYH10 showed the highest 2.34-fold change between glioma and normal brain tissues among all the DRGs." (PMID 38352883, 2024). "Impaired motility was reported in MYH10 depleted lung carcinoma cell line, glioma cells and mouse embryonic fibroblasts." (PMID 35216482, 2022). "Previous studies have shown that MYH10 expression was up-regulated in breast cancer, glioma and meningioma." (PMID 32226520, 2020). "In human glioma cell lines, silencing the MYH10 can inhibit the Wnt/b-catenin pathway to reduce tumor cell migration and invasion, which may regulate the human glioma tumor microenvironment and inhibit epithelial-mesenchymal transition." (PMID 38779358, 2024). "This suggests MYH10 as a potential therapeutic target for glioma." (PMID 38378721, 2024). "Indeed, current findings and our results showed that the downregulation of ACTN4 significantly affected the expression of myosin II in Glioma and MYH10 and myosin light chain (MLC2) in fibroblasts." (PMID 21085685, 2010). "Non-muscle myosin II heavy chain (MYH10) inhibits the Wnt/β-Catenin pathway and decreases glioma cell migration and invasion." (PMID 37628788, 2023).
breast carcinoma (4 papers, 2015 to 2023). "It has been found that the dysregulation of MYH10 participated in the invasion of breast cancer cells." (PMID 34738311, 2021). "For instance, MYH10 could promote metastasis through accelerating initial rates of lamellar spreading in breast cancer." (PMID 34738311, 2021).
lung carcinoma (4 papers, 2015 to 2024). "Although MYH10’s involvement in bladder cancer and lung cancer has been documented, its relationship with THCA remains unexplored." (PMID 38836761, 2024). "In addition, BMP4 was required for normal acinus formation in Matrigel 3-D culture of murine lung cancer cells, which may be mediated by MYH10, a downstream target of BMP4." (PMID 26395571, 2015).
autism (3 papers, 2015 to 2025). Persistent deficits in social interaction and communication and interaction as well as a markedly restricted repertoire of activity and interest as well as repetitive patterns of behavior. "For example, mutations in Grin1, Myh10, Mapk1, and Atp1a3 were found in autism patients or mice." (PMID 32033586, 2020). "A recent study of de novo mutations found in multiple neurodevelopmental disorders revealed that MYH9 is one of only three affected genes shared by autism, schizophrenia and intellectual disability, and de novo mutations for MYH10 are reported for both schizophrenia and autism." (PMID 26542704, 2015).
heart failure (3 papers, 2022 to 2023). Inability of the heart to pump blood at an adequate rate to meet tissue metabolic requirements. "Recently, the upregulation of MYH10 in the cardiomyocytes of adults with heart failure has been reported." (PMID 37372424, 2023).
hepatocellular carcinoma (3 papers, 2021 to 2024). A malignant tumor that arises from hepatocytes. "On the other hand, MYH10 acts as a tumor suppressor and its downregulation is associated with poor outcomes in hepatocellular carcinoma." (PMID 38201971, 2023). "However, a hepatocellular carcinoma (HCC) research study has reported that genomic depletion at the MYH10 locus (17p13.1) is significantly correlated with decreased OS (p = 0.017, HR = 1.55) and DFS (p = 0.003, HR = 1.59) and that the downregulation of MYH10 can promote HCC metastasis." (PMID 38893126, 2024).
Hydrocephalus (3 papers, 2017 to 2023). Hydrocephalus is an active distension of the ventricular system of the brain resulting from inadequate passage of CSF from its point of production within the cerebral ventricles to its point of absorption into the systemic circulation. "Whole exome sequencing (WES) has also identified a rare mutation in MYH10 linked to mental retardation and pathological features of dysplasia, microcephaly, cerebral atrophy, and hydrocephalus." (PMID 32825197, 2020). "Previous studies have shown Myh10 is essential for neural development, with Myh10 null or mutant mice presenting with severe hydrocephalus, disrupted neuroepithelial adhesion, and disorganized neuronal migration." (PMID 36854011, 2023). "By contrast, Myh10 knockout mice develop severe cardiac failure and brain abnormalities, including hydrocephalus and defects in cerebral neuroepithelium and cell migration, which result in late embryonic lethality." (PMID 32825197, 2020). "Myh10 encodes NMHC IIB, the heavy chain component of the NMIIB protein complex, and targeted deletion of Myh10 results in late-gestation lethality with hydrocephalus and cardiac defects." (PMID 29084269, 2017).
Intellectual disability (3 papers, 2020 to 2025). "In 16 individuals, a range of MYH10 variants (missense, frameshift, and in-frame duplications) were associated with developmental delay, intellectual disability, autism spectrum disorder, and corpus callosum agenesis." (PMID 40766181, 2025). "In humans, mutation of MYH10 leads to a severe CNS phenotype characterized by microcephaly, cerebral and cerebellar atrophy and severe intellectual disability." (PMID 32012899, 2020).
microcephaly (3 papers, 2020 to 2025). A congenital or acquired developmental disorder in which the circumference of the head is smaller than normal for the person's age and sex. "While mutations in the MYH10 gene have not been associated with any known human genetic disorders, two human patients with de novo MYH10 mutations presented with clinical phenotypes including microcephaly, congenital diaphragmatic hernia, respiratory failure, and cardiac abnormalities, among others." (PMID 39503257, 2025).
nasopharyngeal carcinoma (3 papers, 2020 to 2023). A carcinoma arising from the nasopharyngeal epithelium. "Loss‐of‐function (LOF) mutations in MYH10 have been proved to promote cell migration and associate with metastasis of nasopharyngeal carcinoma and glioma." (PMID 34738311, 2021). "In contrast, in nasopharyngeal carcinoma, MYH10 was down‐regulated by miR‐200a and was shown to inhibit cell migration and invasion." (PMID 34738311, 2021). "According to previous reports, MYH10 tends to act as an oncogene in tumors, and this study found for the first time that MYH10 has low expression in nasopharyngeal carcinoma." (PMID 32226520, 2020). "In cell function experiments, inhibition of miR-200a can partially reverse the effect of MYH10 on migration and invasion of nasopharyngeal carcinoma cells." (PMID 32226520, 2020). "In our series of clinical specimen verification and in vitro cell experiments, MYH10 has been confirmed to play a consistent role with MYH9 as a tumor suppressor gene in nasopharyngeal carcinoma." (PMID 32226520, 2020). "The expression level of MYH10 in different nasopharyngeal carcinoma cell lines was detected by qRT-PCR, and the results demonstrated that the expression level of MYH10 in 5-8F was the highest, and the expression level in CNE2 and HONE1-EBV cells was low." (PMID 32226520, 2020). "In the relevant cell function experiments, we found that the invasion and migration ability of nasopharyngeal carcinoma cells were enhanced after the MYH10 was reduced in vitro." (PMID 32226520, 2020). "Immunohistochemistry was used to detect the expression of MYH10 in 48 cases of nasopharyngeal carcinoma matched samples." (PMID 32226520, 2020). "In our present study, among 48 pairs of nasopharyngeal carcinoma paraffin specimens, in 77.08% of the normal samples MYH10 is stronger than in the samples of cancer tissues." (PMID 32226520, 2020). "Therefore, we believe that MYH10 is an important pathway for miR-200a to regulate nasopharyngeal carcinoma cell migration and invasion." (PMID 32226520, 2020). "We hypothesized that the inhibitory effect of MYH10 in nasopharyngeal carcinoma was related to the co-polymerization of NMIIA (MYH9) and NMIIB (MYH10) 23-24." (PMID 32226520, 2020). "At present, the role of MYH10 in tumors is rarely reported, and the influence of MYH10 on the occurrence and development of nasopharyngeal carcinoma is an area that has not been studied yet." (PMID 32226520, 2020). "Interestingly, miR200 has been reported to regulate the development of meningiomas by combining MYH10, but there has been no relevant study on this regulatory effect in nasopharyngeal carcinoma." (PMID 32226520, 2020).
anaplastic large cell lymphoma (2 papers, 2021 to 2024). Anaplastic large cell lymphoma (ALCL) is a rare and aggressive peripheral T-cell non-Hodgkin lymphoma, belonging to the group of CD30-positive lymphoproliferative disorders, which affects lymph nodes and extranodal sites. "In the case of anaplastic large cell lymphoma, the genes linked to protein crotonylation are moesin (MSN), myosin heavy chain 9 (MYH9), and myosin heavy chain 10 (MYH10)." (PMID 39513918, 2024).
bladder cancer (2 papers, 2024). "Most disulfidoptosis genes were downregulated in multiple cancer types, including PDLIM1, TLN1, and MYH10 in lung squamous cell carcinoma (LUSC), MYL6 and DSTN in prostate adenocarcinoma (PRAD), and FLNA and ACTB in bladder cancer (BLCA)." (PMID 38862242, 2024).
emphysema (2 papers, 2018 to 2022). "Here the authors show that Myh10 expression is reduced in emphysema patients, and that Myh10 loss of function impairs alveolar formation and lung morphogenesis via upregulation of matrix metalloproteinase activity and altered matrix remodeling." (PMID 30389913, 2018). "Our results from animal models and human patients suggest that structural alterations of the actomyosin network by loss of Myh10 function contribute to the pathogenesis of emphysema." (PMID 30389913, 2018). "In our study, we observed that downregulation of MYH10 expression in human emphysema correlates with disease progression, and Myh10-deficient mice display emphysematous lungs, supporting the notion that Myh10 deficiency might lead to progressive destruction of the lung mesenchyme." (PMID 30389913, 2018). "Notably, our results from animal models and human patients suggest that alterations of the actomyosin network by loss of MYH10 function contribute to the pathogenesis of emphysema and may provide a promising target for preventive care of emphysema." (PMID 30389913, 2018). "As the conditional knockout phenotype in adult mice is histologically reminiscent of emphysema, we first measured the expression levels of MYH10 protein in human lung samples from healthy donors and emphysema patients." (PMID 30389913, 2018). "We next analyzed MYH10 expression in human lung samples from 13 patients with emphysema and 7 healthy donors." (PMID 30389913, 2018). "We found significantly downregulated MYH10 expression in lungs of emphysema patients when compared with healthy donor lungs." (PMID 30389913, 2018). "In the present study of Myh10 deficiency during lung development and homeostasis, excess MMP2 activity and consequent defective ECM remodeling partially recapitulate the pathophysiological features of human COPD, especially emphysema." (PMID 30389913, 2018). "Taken together, these data indicate that MYH10 not only has a critical function in lung alveologenesis, but that it may also play a protective role against the occurrence of emphysema." (PMID 30389913, 2018). "Notably, MYH10 expression is downregulated in the lung of emphysema patients." (PMID 30389913, 2018). "Altogether, our findings reveal critical roles for Myh10 in alveologenesis at least in part via the regulation of ECM remodeling, which may contribute to the pathogenesis of emphysema." (PMID 30389913, 2018).
Hip dysplasia (2 papers, 2023 to 2024). The presence of developmental dysplasia of the hip. "Patients carrying heterozygous pathogenic mutations in MYH10 present with neurodevelopmental disorders and may also have hip dysplasia." (PMID 38952713, 2024).
leukemia (2 papers, 2021 to 2024). A malignant (clonal) hematologic disorder, involving hematopoietic stem cells and characterized by the presence of primitive or atypical myeloid or lymphoid cells in the bone marrow and the blood. "MYH10 is a protein that prevents megakaryocyte ploidization and maturation and promotes the migration of leukemia cells." (PMID 39519080, 2024). "In addition to Myc and Bcl2, other tumor-promoting genes such as Eef2 and Myh10 were upregulated in leukemia cells, whereas tumor suppressors such as Ikzf1, Ikzf2, Arid1b, Arid2, Samhd1, Bach2, and Myo18b were downregulated." (PMID 34907175, 2021).
meningioma (2 papers, 2015 to 2020). A generally slow growing tumor attached to the dura mater. "In meningioma, overexpression of miR-200a can down-regulate the expression of MYH10, leading reduction of the migration and invasion in meningioma cells." (PMID 32226520, 2020). "In the study about meningiomas, miRNA-200 regulates the development of tumor through binding MYH10." (PMID 32226520, 2020). "Moreover, a recent finding suggests that direct targeting of MYH10 itself by miR-200a inhibits cell migration and tumor growth in meningiomas." (PMID 26395571, 2015). "In meningiomas, miR-200a has been shown to inhibit the metastasis and invasion of meningiomas by directly binding 3 'UTRS of MYH10." (PMID 32226520, 2020).
Serous Ovarian Cancer (2 papers, 2024 to 2025). "A serous ovarian cancer research study has reported that MYH10 expression is associated with intraperitoneal metastasis (p < 0.0001) and intestinal metastasis (p = 0.0281)." (PMID 38893126, 2024).
spindle cell tumor (2 papers, 2025 to 2026). "In conclusion, we describe a rare case of CD34-negative, S100-positive spindle cell tumor with MYH10-RET fusion." (PMID 40873555, 2025).
asthma (1 paper, 2025). "Analysis of tight‐junction gene sets revealed the reduced expression of a whole cluster of genes such as OCLN, CLDN3, CLDN4, NRAS, HCLS1, MYH10 in virus‐infected cells from patients with asthma in comparison to the controls." (PMID 39466641, 2025).
bladder urothelial carcinoma (1 paper, 2024). "Single-cell analysis revealed that ACTB, DSTN, and MYL6 were highly expressed in different bladder urothelial carcinoma subtypes, but MYH10 showed a low expression." (PMID 38584831, 2024).
cardiomyopathy (1 paper, 2023). A disease of the heart muscle or myocardium proper. "Our results highlight the role of MYH10 as a key component for sarcomere maintenance in adult cardiomyocyte, including evidence of cardiomyopathy development with their alteration, indicative of sarcomere organization interference." (PMID 37833253, 2023).
Cognitive impairment (1 paper, 2022). Abnormal cognition is characterized by deficits in thinking, reasoning, or remembering. "Therefore, we hypothesized that MYH10, PAK4, and PIKfyve might be the targets of obesity-induced cognitive impairment, providing new ideas, and directions to understand the pathogenesis of obesity-induced cognitive impairment." (PMID 36408417, 2022).
endometrial adenocarcinoma (1 paper, 2023). "Of particular interest is myosin heavy chain 10 (MYH10), since silencing its expression in human endometrial adenocarcinoma (HEC-1-B) cell culture, significantly attenuates cell migration and invasion capacities." (PMID 37895099, 2023).